CD4 (CD4 molecule)
Diseases named in the same sentence as CD4 in open-access papers (continued):
Sharing a sentence is not in itself a finding about the gene and the disease.
tuberculosis (continued). "Antiretroviral therapy has been shown to substantially decrease tuberculosis incidence in persons living with HIV, particularly when it is initiated while CD4 counts are still comparatively high." (PMID 24937804, 2014). "In univariateanalysis, sex, CD4 count, BMI, WHO stage, employment status, smoking status and presence of tuberculosis at initiation ofART were significant predictors of recovery from anaemia." (PMID 25722787, 2014). "Compared to persons with tuberculosis who survived, those who died had lower median CD4+ lymphocyte count at ART initiation (45 vs. 66 cells/mm3; P=0.02) and before tuberculosis diagnosis (59 vs. 85 cells/mm3; P=0.01)." (PMID 24066096, 2013). "In conclusion, our results indicate that independent of the immunosuppression profile, HIV-TB patients under tuberculosis treatment and HAART are able to recover the CD4+ T cell counts and control of viral replication and immune activation over time." (PMID 23840403, 2013). "Among HIV-infected persons who develop tuberculosis before starting ART and have < 50 CD4+ lymphocytes/mm3 at the time of tuberculosis diagnosis, starting of ART within 2-4 weeks of initiating anti-tuberculosis therapy significantly improves survival." (PMID 24066096, 2013). "Of 253 patients who met inclusion criteria, median CD4+ lymphocyte count at ART initiation was 64 cells/mm3, 171 (68%) received >180 days of anti-tuberculosis therapy, 168 (66%) initiated anti-tuberculosis therapy before ART, and 43 (17%) died." (PMID 24066096, 2013). "In addition, the finding that the circulating Treg cells in the peripheral blood declined progressively by 2 months of anti-TB treatment is also in agreement with a recent report on CD4+CD25+FoxP3+ T cells in human tuberculosis." (PMID 23826366, 2013). "When only M. tuberculosis culture-positive TB cases were selected for analysis, retreatment TB patients were found to have higher frequencies of CD244/2B4-expressing antigen-responsive CD4+ T cells than latent infection individuals (p = 0.0098) and new TB patients (p = 0.0339) as well." (PMID 23638187, 2013). "The cohort was immunosuppressed at ART initiation, with a median CD4 count of 82 cells/mL (IQR 30–151), 45.7% with WHO stage III/IV, and 19.9% with a tuberculosis diagnosis." (PMID 24069036, 2013). "Mortality in patients with CD4 count <100 cells/μl, WHO stage III and IV, and the presence of tuberculosis at ART initiation was 47.66 (95% CI: 41.65–54.55), 60.40(95% CI: 51.02–71.50) and 54.61(95% CI: 46.01–64.80) per 100 person years, respectively." (PMID 23527132, 2013). "In those with active tuberculosis, >17.3% of PPD-specific CD4+ TNF-α-only-secreting cells were CD45RA−CCR7−CD127−, and this phenotype was therefore strongly associated with activated infection." (PMID 23966657, 2013). "The frequency of PPD-specific CD4+ IFN-γ only, TNF-α only, and IFN-γ/TNF-α-dual-secreting cells was higher in active tuberculosis compared with latent tuberculosis infection (P = .003.002, and .002, respectively)." (PMID 23966657, 2013). "IFN-γ stimulated responses are lowered in tuberculosis (TB), while expression of Suppressor of Cytokine Signaling (SOCS) molecules – 1 and 3 and CD4+CD25+FoxP3+T regulatory cells is increased." (PMID 23320781, 2013). "CD4 count <200 cells/μL (HR = 5.02; 95% CI: (2.03, 12.39), and the presence of HIV-tuberculosis coinfection at ART initiation (HR = 2.91; 95% CI: (2.11, 4.02) were significantly associated with mortality." (PMID 24052883, 2012). "These are the patients in whom tuberculosis diagnosis is so challenging such that, in the absence of suitable diagnostic assays, empirical treatment has been suggested as a strategy to reduce the high mortality of patients with very low CD4 cell counts in settings with the highest disease burden." (PMID 22015305, 2012). "Thus, tuberculosis (TB) progression and the degree of effector CD4 T cell differentiation are interrelated, but the relationships are complex and not well understood." (PMID 22937086, 2012).
tuberculosis (continued). "The mean CD4+ lymphocyte count of HIV mono-infected participants were 296 ± 192 Cells/mm3 and tuberculosis-HIV co-infected patients had mean CD4+ lymphocyte count of 199 ± 149 Cells/mm3 with p value of 0.007." (PMID 22738361, 2012). "Complete results from all tests were available for 516 patients (median CD4 count, 169·5 cells per μL; IQR 100–233), including 85 culture-positive tuberculosis, 24 of whom (28·2%, 95% CI 19·0–39·0) had sputum smear-positive disease." (PMID 22015305, 2012). "In tuberculosis and leprosy, similar amounts of IFN-γ were produced by CD4+ and CD8+-cells as detected by intracellular-staining using flow cytometry." (PMID 23028529, 2012). "Although antiretroviral therapy (ART) is known to be associated with time-dependent reductions in tuberculosis (TB) incidence, the long-term impact of ART on incidence remains imprecisely defined due to limited duration of follow-up and incomplete CD4 cell count recovery in existing studies." (PMID 22479548, 2012). "Continuing our studies, we wished to investigate the relationship between immune status and adrenal hormone levels during HIV and tuberculosis co-infection, we performed correlation analyses between DHEA-s or cortisol levels and CD4+ T cell counts." (PMID 22431997, 2012). "With regards to tuberculosis, we are unaware of previous work investigating IL-13 BAL levels but increased IL-4 secretion from both CD4+ and CD8+ T-cells in active pulmonary tuberculosis has been shown compared to those with latent infection." (PMID 22815689, 2012). "Risk of death was also associated with being injecting drug users as well as to a lower CD4 cells count at the time of tuberculosis diagnosis and MDR tuberculosis." (PMID 22489253, 2012). "Moreover, the CD4+ T cell-derived transcriptional signatures of distinct latency populations might be helpful to identify subsets of latent individuals that produce protective responses against tuberculosis." (PMID 22719887, 2012). "Together with activation of CD4+ and CD8+ T-cells, higher frequencies of both αβ and γδ DN T-cells from tuberculosis patients also express the chronic activation marker HLA-DR." (PMID 23239994, 2012). "tuberculosis modulates MHC class II antigen presentation, wefocused on in vivo activation of CD4+ T cells in the lungs." (PMID 21637811, 2011). "Baseline CD4 cell count, WHO stage at initiation, presence of tuberculosis and duration of follow up all differed significantly between male and female patients." (PMID 22050673, 2011). "Although spleen CD4+ and CD8+ T cells showed maximal tuberculosis antigen-specific activation by 8 weeks, macrophage activation in lungs, lymph nodes and spleen did not peak until 12 weeks." (PMID 22645653, 2011). "For HIV-infected patients, CD4 T cell counts and HIV viral loads have been identified as significant factors of mortality in tuberculosis." (PMID 21931610, 2011). "In HIV-infected patients with CD4 < 100, HAART should be withheld until active tuberculosis has been completely treated." (PMID 17678548, 2007). "This primarily includes HIV viral load testing, but should also consider additional monitoring tools, such as CD4, to identify advanced HIV disease, tuberculosis screening and diagnosis, and other infectious disease screenings and testing, depending on prevalence rates where the children reside." (PMID 41236077, 2025). "The results indicated that the frequencies of cytokine-secreting Mtb-specific CD4 T cells with the CD38+CD27– phenotype clearly distinguished individuals with active tuberculosis from those without the disease." (PMID 40406513, 2025). "In contrast, patients with tuberculosis had the lowest median CD4 count of 83 cells/mm3 (IQR 59–85), and none were virally suppressed, although 66.7% (n = 4/6) were on ART." (PMID 41200369, 2025).
tuberculosis (continued). "A study of tuberculosis in chimeric mice containing MHCII+ and MHCII– cells found that MHCII– cells contained more Mtb bacilli than MHCII+ cells from the same animal, a difference that was abrogated by CD4+ T cell depletion." (PMID 40489538, 2025). "Most notably, IFN-γ production is not sufficient to explain CD4+ T cell-mediated protection against tuberculosis." (PMID 40489538, 2025). "There is convincing evidence that ongoing HIV replication, including suboptimal HIV control with antiretroviral therapy, is an important risk factor for tuberculosis development in PLHIV, independent of CD4 cell count." (PMID 40062355, 2025). "For example, multifunctional CD4+ and CD8+ T cells against Mycobacterium tuberculosis are induced when primed with specific recombinant Bacillus Calmette-Guérin and boosted with plasmid DNA as a strategy to prevent tuberculosis." (PMID 40487437, 2025). "In patients with active tuberculosis, the cross-linking activation of the CD244/2B4 signaling pathway inhibits the production of IFN-γ, possibly due to its inhibitory effect on Mycobacterium tuberculosis antigen-specific CD4+ T cell function." (PMID 38980684, 2025). "The WHO guidelines recommend starting ART within 2 weeks for PWH with tuberculosis at a non-neurological site, independent of CD4 cell count." (PMID 40158188, 2025). "In contrast, among 642 PLHIV without TPT, one with an indeterminate QFT+ and 3/30 individuals with a positive QFT+ developed active tuberculosis; all had detectable HIV-replication and low CD4 T-cell counts (incidence 4.1 (95% CI (1.3–12.4) per 100 person-years)." (PMID 40823191, 2025). "Eligibility criteria included antiretroviral therapy for at least 3 months, HIV viral load of less than 200 copies per mL, CD4 counts of 200 cells per μL or higher, and previous completion of tuberculosis preventive therapy and no tuberculosis history." (PMID 40614747, 2025). "In contrast, in mice lacking the AhR in macrophages, we observed a significant increase in T-cell infiltration, along with increased cytokine secretion by CD4+ and CD8+ T cells, ultimately promoting an adaptive immune response against tuberculosis and reducing the bacterial load." (PMID 39438693, 2024). "Patients without tuberculosis and had not recovered their CD4 count were 1153 (46%), 594 (24%) recovered their CD4 count and 257 (10%) died before reaching a CD4 count of more than 500 cells/mm3." (PMID 39058196, 2024). "Third, despite adjustment for potential confounders (e.g. age, sex, country, baseline CD4+ T-cell count and excluding participants with chronic hepatitis B or tuberculosis), we cannot rule out residual confounding effects on microRNA levels." (PMID 38300257, 2024). "Additionally, correlation analysis of CXCL9/10 mRNA levels and CD4+ and CD8+ T-cell infiltration in the lungs of tuberculosis patients revealed the significant role of CXCL9/10 expression in T-cell infiltration." (PMID 39438693, 2024). "In contrast, the association between CD4+/CD8+ < 1 and tuberculosis severity was found to be nonsignificant." (PMID 39086487, 2024). "Pregnant women with active tuberculosis and HIV infection should start ART immediately, regardless of CD4 cell count and tuberculosis sites, in order to control the virus rapidly and reduce HIV transmission to newborns." (PMID 38675837, 2024). "Finally, four variables were identified as independent predictors of second-line ART treatment failure: poor ART drug adherence, CD4 count < 100cells/mm3 at change, advanced WHO clinical stage and tuberculosis co-infection." (PMID 38652716, 2024). "The median level of the CD4+ cell count in the rs4986790-AA (TLR4) genotype carriers was 1.13/2.23 times lower than in the rs4986790-AG/GG (TLR4) genotype carriers in HIV patients and HIV–tuberculosis coinfected patients, respectively." (PMID 37606452, 2023).
tuberculosis (continued). "In subset of HIV-1 co-infected patients for whom the absolute CD4 count was available, the trend between neutralising antibody level and CD4 was not significant (r = 0.21 p = 0.34) and patients with tuberculosis (pink) did not form a distinct subgroup." (PMID 36635274, 2023). "ID93+GLA-SE can stimulate CD4+ T cells to secrete high levels of Th1 cytokines, resulting in protective anti-tuberculosis effects in BCG-immunized and non-immunized mice and guinea pigs." (PMID 37631874, 2023). "Tuberculosis and pneumonia were consistently the leading immediate causes of death in PLWH, regardless of the VL and CD4+ count." (PMID 37153012, 2023). "Numerous studies have explained active TB progression in terms of host-environment interactions when the patient is exposed to M. tuberculosis via droplets or aerosols; primary infection occurs according to host CD4 T lymphocyte and macrophage immune responses." (PMID 38001469, 2023). "By directly inducing CD4+ T lymphocyte depletion or by establishing a chronic inflammatory environment, HIV is the main driver of Mtb proliferation and the conversion of latent Mtb infection to tuberculosis." (PMID 37110276, 2023). "The multivariable regression model (Enter method) included age groups, sex, marital status, education, occupation, BMI categories, alcohol intake, co-morbidities (diabetes mellitus, renal disease, and tuberculosis), and HIV related factors (WHO staging of HIV, viral load, and CD4 counts)." (PMID 37908015, 2023). "However, paradoxical tuberculosis-associated immune reconstitution inflammatory syndrome (TB-IRIS) complicates treatment in 18% (95%CI 16–21%) of patients, with percentages up to 50% in high risk groups (i.e., low CD4 counts and a short interval between starting anti-tuberculosis treatment and ART)." (PMID 36275235, 2022). "BCG induces strong CD4+ T cell responses but relatively weak CD8+ T cell responses in contrast to M. tuberculosis, which induces both strong CD4+ and strong CD8+ responses, which may be important for protective immunity to tuberculosis." (PMID 35632582, 2022). "Presence of opportunistic infection, no formal education, low CD4 count and patients having respiratory infection like tuberculosis are important predictors of treatment failure among HIV patients." (PMID 36962756, 2022). "Latest guidelines recommend that ART should be started as soon as possible within 2 weeks of initiating tuberculosis treatment, regardless of CD4+ T-cell count." (PMID 36008855, 2022). "Of the total of children living with HIV, 49 (13.50%), 61 (16.80%), 81 (22.31%), 40 (11.02%), and 39 (10.74%) had HGB (Hemoglobin) levels of 10 mg/dl, CD4 counts or % below the threshold, WHO stages III & IV, TB (Tuberculosis), and treatment failure in the follow-up period." (PMID 35031007, 2022). "When comparing patient characteristics of DTG with both EFV groups, there were significant differences in age group, sex and site of tuberculosis disease, and when comparing DTG with the H‐EFV group, there were also significant differences in timing of ART initiation and CD4 count." (PMID 35848120, 2022). "CD4 T cell phenotyping-based blood assays have the potential to meet WHO target product profiles (TPP) of non-sputum-biomarker-based tests to diagnose tuberculosis (TB)." (PMID 34162973, 2021). "However, there is evidence that patients with active tuberculosis (TB) achieve immune suppression due to increased expression of CD244 by many immune cells, including CD4+ T cells and myeloid-derived suppressor cells (MDSCs)." (PMID 33841431, 2021). "In the HIV-1 infected outpatient control group without active tuberculosis, the number of nodal connections with IL-17A was significantly higher in those with lower CD4 cell counts and unsuppressed viral loads." (PMID 34386782, 2021).
tuberculosis (continued). "In antiretroviral therapy cases not yet initiated, with CD4+ T lymphocytes counting lower than 50 cells/mm3, it is recommended to start treatment for tuberculosis first and introduce ART within up to two weeks." (PMID 34008717, 2021). "Moreover, the World Health Organization (WHO) recommends the tuberculosis lipoarabinomannan antigen, shown to increase diagnoses and reduce mortality rates in PLHIV with CD4 cell counts <100/μL." (PMID 34910173, 2021). "Being anemic, WHO stages III and IV, not on CPT, CD4<200cells/μl, and being male were significant predictors of tuberculosis." (PMID 33632342, 2021). "In tuberculosis and PCM, an effective CD4 T cell response was essential to control the diseases." (PMID 33302372, 2020). "A limitation of this study was that neither the key pointers of the illness progression, such as the CD4 count and viral load, nor data on medication for tuberculosis were assessed." (PMID 32935068, 2020). "In addition, changes in the mannosylation pattern of the M. bovis BCG Apa have been shown to alter its ability to stimulate CD4+ and CD8+ T-lymphocyte responses involved in the protective properties of the BCG vaccine against tuberculosis." (PMID 32443484, 2020). "The use of urinary LF-LAM was the predictor with the best ability of creating pure groups (either with or without tuberculosis); classifying almost 25% of the study sample (75% of which were true positives) regardless of their CD4 cell count." (PMID 36325129, 2020). "Older participants were less likely to experience a tuberculosis event, as were those with a lower HIV viral load or higher CD4+ T-cell count over follow-up, those who initiated cART in more recent years and those who had been on cART for a longer period of time." (PMID 32501837, 2020). "Severity of PTB has been shown to be mediated by immune mechanisms and it has been shown that HIV infected patients having lower CD4 counts usually present with non-cavitatory tuberculosis." (PMID 32765475, 2020). "A new treatment criterion (CD4 count ≤ 200 cells/mm3 or HIV clinical stage III/IV irrespective of CD4 count, including coinfections such as tuberculosis) for ART initiation was adapted." (PMID 32257156, 2020). "A previous analysis of the UK Collaborative HIV Cohort (UK CHIC) study, including data from 1996 to 2005, showed high incidence of tuberculosis among people with HIV of Black African ethnicity, despite the widespread availability of cART and improved CD4+ cell counts." (PMID 32501837, 2020). "Tuberculosis patients and HCs had comparable proportions of PPD- or E6/C10- specific CD4+ T cells." (PMID 31333654, 2019). "Still, we describe simple patterns for the two diseases to help clinicians distinguish between histoplasmosis and tuberculosis, regardless of the CD4 count level." (PMID 31847076, 2019). "The most common predictors are age, gender, being orphan, time from ART initiation, poor adherence to ART failure, nevirapine (NVP)-based regimen, drug side-effects, drug toxicity, nutritional status, pretreatment CD4 count, WHO clinical stage and tuberculosis co-infection." (PMID 31042743, 2019). "In most studies both in our country and others show that low CD4 count at ART initiation and occurrence of severe opportunistic infection (like; tuberculosis and chronic diarrhea) were significant predictors of first-line ART treatment failure, unlike the current study." (PMID 31042743, 2019). "to 1.0) kg/m2, median CD4 102 (IQR: 38 to 239) cells/μL, median HIV‐RNA was 5.5 log (IQR: 5.0 to 5.8), 311 (68%) patients had pulmonary tuberculosis only, and 308 (68%) had bacteriologically‐confirmed tuberculosis." (PMID 31339004, 2019). "Lessons learned from POC CD4 scale-up and invalid test patterns will be useful to inform the scale up of other POC devices, such as early infant diagnosis, viral load testing, hepatitis, and tuberculosis, in the future." (PMID 31276477, 2019).